CD4 (CD4 molecule)
Diseases named in the same sentence as CD4 in open-access papers (continued):
Sharing a sentence is not in itself a finding about the gene and the disease.
periodontitis (continued). "The two-way relationship between T2DM and chronic periodontitis, with senescent CD4+CD28- T cells potentially serving as mediators, is a good example." (PMID 38586464, 2024). "In different periodontitis subtypes (cluster 1 and cluster 2), naive B cells, memory B cells, plasma cells, activated memory CD4 T cells, gamma delta T cells, and gamma delta T cells were found." (PMID 38308306, 2024). "The RANKL/OPG axis, formed by RANKL expression on CD4+ T cells and OPG, is directly correlated with bone homeostasis, and an increased RANKL/OPG ratio is associated with chronic periodontitis and the progression of apical chronic periodontitis." (PMID 39684494, 2024). "Oral inoculation of bacteria in mice stimulates the production of IL-22 through increased numbers of IL-22-expressing CD4+ T-cells in periodontitis-affected tissues." (PMID 38919613, 2024). "Naïve B cells, neutrophils, plasma cells, and activated memory CD4 T cells were significantly enriched in periodontitis samples, and 25 drugs targeting 4 DE-IRGs were predicted." (PMID 39917706, 2024). "Based on a similar disease, human chronic periodontitis, an increase in CD4+ cells should have been expected." (PMID 39711796, 2024). "Human studies indicate an approximately 25% decrease in CD4+ T-cells in human subjects and a similar reduction of over 30% in mouse periodontitis models." (PMID 38919613, 2024). "In our case, the patient’s CD4+/CD8+ (CD3+CD4+/CD3+CD8+) ratios were low, indicating that the patient’s ability to defend against infection was impaired, and the risk of periodontitis increased." (PMID 37773856, 2023). "To validate the contribution of the activated JAK/STAT3 signaling on the impaired immune modulation ability of BM-MSCs from periodontitis mice, we additionally treated these BM-MSCs with C188-9 before and during their co-culturing with the CD4+ T cells." (PMID 37490712, 2023). "In our results, a CAL > 3 mm and CAL > 5 mm, reflecting the severity of periodontitis, were higher in the group with low levels of CD4+ T cells than in the group with higher levels." (PMID 38102603, 2023). "In periodontitis samples, Plasma cells, Neutrophils, T cells CD4 naive, Macrophages M0 were significantly increased compared to normal samples." (PMID 37369700, 2023). "In terms of T-cells, periodontitis-affected tissues had a larger proportion of activated CD4 memory T-cells, whereas healthy tissues had a lower number of regulatory T-cells." (PMID 39916927, 2023). "In this study, CCDC69 and CXCL12 had a significant positive correlation with central memory CD4+ T cells and immature B cells in both periodontitis samples and IgAN samples." (PMID 36793719, 2023). "Th17 lymphocytes have been described as a subset of CD4+ T cells with the capacity to induce osteoclast differentiation and activation during the pathogenesis of periodontitis." (PMID 35269683, 2022). "A study detected that the difference in immune cells between healthy periodontal tissues and periodontitis mainly included B cells, activated CD4+ memory T cells, resting dendritic cells, and neutrophils." (PMID 36072904, 2022). "Although there are currently no drugs that target CD4 to reduce inflammation or the function of CD4+ T cells, the identification of CD4 as a hub gene marks the importance of T helper cells in the inflammatory response during periodontitis." (PMID 35628390, 2022). "The role of T cells was still controversial, and there was little specific evidence to reveal the function of specific CD4+T cell subsets in periodontitis." (PMID 36131931, 2022). "Since different mTOR complexes play distinctive roles on CD4+ T cell fate determination, explicit deletion or activation of mTORC1 and mTORC2 has been recommended to explore their exact roles on periodontitis." (PMID 35222410, 2022).
periodontitis (continued). "Studies have shown that CD4+ helper T cells (Th), which release cytokines that recruit and activate other immune cells, play a major role in alveolar bone destruction during periodontitis." (PMID 35628390, 2022). "The situation in early periodontitis reflected this effect of IL-17, although it has been shown that in the gingiva the IL-17 production by CD4+ αβ T cells plays an important role that seems to be more decisive than the one by γδ T cells." (PMID 35298525, 2022). "Higher percentages of CD19 expressing B cells, and lower percentages of CD3 and CD3 + CD4+ expressing T cells were observed in immune cells derived from gingival tissue of periodontitis patients when compared to those of healthy individuals." (PMID 33672708, 2021). "As for the memory T cell subsets, a significant increase in the proportion of CD4(+)CD69(+) CD103(-) memory T cells was observed in periodontitis tissues compared with healthy gingiva." (PMID 34868054, 2021). "CD4(+) memory T cells from periodontitis tissues produced either IL-17 or IFN-γ whereas CD8(+) memory T cells produced only IFN-γ." (PMID 34868054, 2021). "As documented before, when we analyzed the frequency of Foxp3+ cells among all CD4+ cells in cervical lymph nodes, the percentage increased in periodontitis as a feedback mechanism in the inflammatory process." (PMID 34012448, 2021). "The percentage of Foxp3+ cells in the CD4+ gate was increased in animals with periodontitis compared to both baseline and RvE1-treated animals (both ≈70% difference, P<0.001)." (PMID 34012448, 2021). "It has been reported that the percentage of IL-17 producing CD4+T cells was higher in periodontitis lesions than in healthy tissues and gingivitis lesions." (PMID 33981487, 2021). "Animals with periodontitis showed a reduced frequency of CD4+ T cells within all cells in the lymph nodes as a direct result of increased organ size (lymphadenomegaly) compared to baseline (65% less, P<0.001) and RvE1-treated animals (42% less, P<0.01)." (PMID 34012448, 2021). "The 3D-exos contained more miR-1246, which can mediate CD4+ T-cell differentiation by decreasing Nfat5, thereby relieving Th17 cell/Treg imbalance and alleviating periodontitis." (PMID 34907166, 2021). "We detected a significant increase of both the percentage of CD4+Rorγt+ cells within the CD4+ compartment and the total number of CD4+Rorγt+ cells at days 10 and 15 post-periodontitis induction." (PMID 33149125, 2020). "We have shown previously that Th17 cells are predominant in the early adaptive CD4+ T cell response to Pg in an oral model of periodontitis, and that this response is critically dependent on LCs." (PMID 32391008, 2020). "T cells can be activated in response to oral bacterial antigens, and CD4+ T cells play key roles in the development of a mouse model of periodontitis." (PMID 32328131, 2020). "Considering the roles of DCs for cytokine production and differentiation of CD4+ T cells, DCs are reckoned to be the bridge between the innate and adaptive immune responses in periodontitis." (PMID 32328131, 2020). "These concordant evidences therefore support that having CD4 cells less than 200 is a strong predictor of periodontitis in population living with HIV." (PMID 33308188, 2020). "In the present study, the F4/80+, CD206+, and CD4+/Foxp3+ cells were monitored in the mice gingival tissue from the healthy (H), periodontitis (P), and cell injection (CI) groups." (PMID 33195441, 2020). "Accordingly, we detected a higher frequency and increased the total number of CD4+Foxp3+ cells at day ten after the induction of periodontitis." (PMID 33149125, 2020). "Specific genetic depletion of RANKL production in osteoblasts and periodontal ligament cells during ligature-induced periodontitis reduces the alveolar bone resorption in an even greater extent that the RANKL depletion on CD4+ cells." (PMID 31379856, 2019).
periodontitis (continued). "The results of our study showed an increase in the proportions of natural Tregs (CD4+ CD25+ Fox P3+) in the chronic periodontitis group compared to the gingivitis and healthy tissue groups." (PMID 31183266, 2019). "The results of our study showed an increase in the proportion of nTregs (CD4+ CD25+ Fox P3+) in the chronic periodontitis group compared to the gingivitis and healthy tissue groups." (PMID 31183266, 2019). "For instance, there is a higher frequency of CD4+ CD25+ CTLA-4+ Tregs in periodontitis biopsies than in gingivitis." (PMID 29805313, 2018). "Specifically, gingiva of RvD2-treated mice contained less CD4+ T-cells and Foxp3+CD4+ Treg cells, which are known to accumulate in the gingiva during inflammation and experimental periodontitis." (PMID 29922275, 2018). "In a murine model of periodontitis, Am80 reduced the percentage of CD4+ RORγt+ Th17 lymphocytes and increased the percentage of CD4+ Foxp3+ Tregs in the gingival tissues, cervical lymph nodes, and spleen." (PMID 29805313, 2018). "We first investigated pathogenic T cell populations in periodontitis by evaluating IL-17A and IFN-γ producing CD4+T cells in CP patients." (PMID 28229025, 2017). "In 2 of 4 subjects with low viral loads, high CD4 levels, and periodontitis, C. albicans was predominant and S. cerevisiae was only a minor component." (PMID 24864144, 2014). "According to the fact that immune response to P.gingivalis in atherosclerotic patients is stronger than periodontitis patients, we believe the decrease of CD4+CD25+FOXP3+ T cells be related with the increased response towards P.gingivalis infection." (PMID 24466164, 2014). "In spite of this knowledge, there is not solid evidence on the specific role of T cell subsets in periodontitis and the signalling process to activate or regulate them, with the exception that CD4+ T cells are induced by P. gingivalis to express RANKL." (PMID 25057495, 2014). "Of the multiple types of CD4+ T cells (Th1 Th2, Th17, and Tregs), Th2 cells are thought to dominate over an initial Th1 response in progressive periodontitis." (PMID 25057495, 2014). "In a murine model of periodontitis, adaptive immune responses, primarily through effector CD4+ T helper cells, were found to contribute extensively to P. gingivalis-induced alveolar bone loss." (PMID 23945018, 2013). "Published data suggest possible opportunistic behavior of E. gingivalis because the high parasite frequency and advanced periodontitis have been correlated with low CD4+ lymphocyte counts and with immunosuppression." (PMID 24376598, 2013). "Furthermore, local administration of these CD73+ Treg‐derived EVs in a murine periodontitis model reduced activated CD4+ T cell infiltration, decreased IL‐17A and RANKL expression, and attenuated osteoclast‐mediated alveolar bone loss." (PMID 40620009, 2025). "However, a significantly higher CD73 MFI signal was observed in CD4+ T cells infiltrating periodontitis‐affected mice treated with RATEVs compared to untreated controls." (PMID 40620009, 2025). "CD4+ T cells are key determinants of tooth‐supporting bone resorption during periodontitis." (PMID 40620009, 2025). "During periodontitis progression, innate immune cells detect bacterial antigens in subgingival plaques, migrate to cervical lymph nodes, and present these antigens to activate T cells, leading to CD4+ T cell proliferation." (PMID 40541947, 2025). "We observed that the periodontitis group had a higher concentration of activated CD4 T cells, which led us to hypothesize that these cells might be engaged in immune killing during ICD development." (PMID 39555084, 2024). "CD8+ T-cells are fewer in number than CD4+ T-cells in periodontitis lesions." (PMID 38919613, 2024). "However, immunohistochemistry of lesions in advanced periodontitis showed the presence of CD4+ T cells co-expressing IFN-gamma suggesting the presence of Th1 T cells." (PMID 39253090, 2024).
periodontitis (continued). "Conversely, the proportions of activated memory CD4 T cells, regulatory T cells (Tregs), activated NK cells, resting dendritic cells, activated dendritic cells, and resting mast cells were significantly lower in patients with periodontitis." (PMID 38308306, 2024). "Our findings also show that periodontitis is associated with an impaired adaptive immune response not only in CD4 + T-cells but also in CD8 + T lymphocytes, with a high degree of differentiation and, therefore, excessive functional responsiveness." (PMID 38451305, 2024). "In terms of Absolute Count, having chronic periodontitis led to a decrease in CD39 + activated CD4 regulatory T cell Absolute Count (Beta = -0.12 [-0.10, -0.13], P = 0.03) and CD39 + secreting CD4 regulatory T cell Absolute Count (Beta = -0.13 [-0.12, -0.14], P = 0.02)." (PMID 39014403, 2024). "Significant alterations in immune cell ratios were observed between healthy individuals and periodontitis patients, with increased levels of naive B cells, plasma cells, native CD4+ T cells, activated memory CD4+ T cells, γδT cells, and neutrophils in periodontitis tissues." (PMID 39045324, 2024). "Furthermore, some other studies have shown that IL-10 produced by B cells can alleviate alveolar bone resorption and regulate the local CD4+ T cell population, suggesting that B cells have some potential for regulating periodontitis." (PMID 37226540, 2023). "However, the population of TH17 cells was significantly elevated in the periodontitis group, while the amount of CD4+ regulatory T-cells decreased significantly when compared to healthy animals." (PMID 39916927, 2023). "All three CD4+ T lymphocyte subsets play essential roles during periodontitis pathogenesis." (PMID 36761739, 2023). "Recently, it was reported that CDT genotoxin, a virulence factor present in pathogenic Gram-negative bacteria closely linked to periodontitis, is able to induce senescence in CD4+ T lymphocytes." (PMID 35269683, 2022). "CD4+T cells play a significant role in periodontitis and orthodontic tooth movement." (PMID 35280902, 2022). "Mainly, senescence of CD4+ T lymphocytes appears to be a common feature of osteoimmunological diseases, suggesting that CD4+ T cell senescence may also occur in the context of periodontitis." (PMID 35269683, 2022). "However, while IL-17 was reported to be enhanced in human periodontitis, it was shown to be mainly produced by CD4+ αβ T cells (Th17 cells) in health and periodontitis, while γδ T cells only showed a minor contribution." (PMID 35298525, 2022). "The active CD4 T cell was positively correlated with activated CD8 T cell in periodontitis." (PMID 36545026, 2022). "Taken together, these data allow us to suggest that senescence within the periodontitis-related CD4+ T lymphocyte compartment may partly explain the Th17/Treg imbalance that results in osteoclast/osteoblast uncoupling and favors alveolar bone resorption." (PMID 35269683, 2022). "Furthermore, an increased number of IL‐17A+ cells and decreased Foxp3+ cells per bone surface were observed in OVX/periodontitis rats and this skewed CD4+ T cell‐mediated osteoimmune response was rescued by the administration of probiotics." (PMID 34101283, 2021). "Previous studies identified an association between CD4+CD25+Treg and periodontitis." (PMID 34234776, 2021). "Collectively, RvE1 rescued the periodontitis-induced changes in CD4+ cells." (PMID 34012448, 2021). "Actinobacillus actinomycetemcomitans, a Gram-negative anaerobic microorganism that causes periodontitis in humans, activates CD4+ cells in periodontitis tissues and cause local alveolar bone destruction." (PMID 34539410, 2021). "Results showed that in this environment of persistent dysbiosis as occurs in periodontitis, the CD4+ T lymphocyte-mediated immune response evolves from one initially dominated by IL-17A to one that is predominantly IFN-γ-producing, in a response generated de novo by Th1 cells." (PMID 33363538, 2020).
periodontitis (continued). "Accumulated evidence has indicated that DCs and CD4+ T cells from spleen can be used to detect the role of the host immune response on periodontitis and DCs from mouse spleen could exert an antigen‐presenting function to induce CD4+ T responses as well." (PMID 32406154, 2020). "What is unknown in periodontitis is whether differentiated CD4+ T cells modulate their response by re-programming cytokine expression when encountering persistent dysbiosis and heightened ability of pathobionts to cross the oral mucosal barrier." (PMID 32391008, 2020). "Interestingly, severely immune-compromised patients and men are vulnerable to periodontitis, thereby highlighting the need for clinicians to refer patients for regular periodontal screening especially male patients and those with low CD4." (PMID 33308188, 2020). "Moreover, the migration of CD4+ CD25+ T cells to periodontitis that affected gingival tissues seemed to be dependent on CCL17 and CCL22 expression by the local inflammatory infiltrate, which recruits Treg expressing CCR4 or CCR8." (PMID 29805313, 2018). "Indeed, a detrimental role of gingival CD4+ T cells in alveolar bone destruction under chronic periodontitis has been steadily proposed since the seminal work of Penninger’s group." (PMID 28270813, 2017). "An early seminal study using NOD/SCID mice transplanted with human peripheral blood lymphocytes as a model of periodontitis showed that human CD4+ T cells in the periodontium triggered local alveolar bone destruction by secreting osteoprotegerin ligand, also known as RANKL." (PMID 28270813, 2017). "In our study, nearly half of HIV-positive FSW had CD4 count <350 cell/mm3, which might partly explain the high prevalence of periodontitis." (PMID 26631015, 2015). "We hypothesized that there would be differences in the percentage of CD4+ T-cells producing IL-4 between patients suffering from aggressive periodontitis compared to patients with chronic periodontitis and healthy controls." (PMID 25299619, 2014). "However, S. cerevisiae (not C. albicans) was the only fungal species detected from the LGE subject and 2 of 4 severe subjects with high viral loads, low CD4 levels, and periodontitis." (PMID 24864144, 2014). "Although virulence factors of P. gingivalis are hypothesized to contribute to the pathogenesis of periodontitis, it is unclear whether the local CD4+ T-cell-mediated response they elicit prevents or contributes to periodontal bone destruction." (PMID 23945018, 2013). "Even severely immunocompromised HIV-seropositive subjects with chronic periodontitis who are using HAART and with low CD4+ T-cell counts demonstrate similar periodontopathic bacteria in their subgingival microbiota to HIV-seronegative subjects with chronic periodontitis of a comparable degree." (PMID 22970354, 2012). "In addition, higher levels of IL-10 were observed in the gingival crevicular fluid and in the inflamed tissue of periodontitis patients along with the presence of putative IL-10-producing cells, such as CD4+CD25+FoxP3+ regulatory T cells, in the inflammatory infiltrate of gingival tissues." (PMID 39253090, 2024). "However, whether mTOR signaling is involved in periodontitis through regulating CD4+ T cell differentiation remains unknown." (PMID 35222410, 2022). "Therefore, up-to-date accumulated evidence suggests that senescence in CD4+ T lymphocytes could play a critical role during the pathogenesis of periodontitis." (PMID 35269683, 2022). "Likewise, recent studies using the Tcrd-GDL mice and ligature-induced periodontitis model showed that the IL-17 production by CD4+ αβT cells (Th17 cells) in the gingiva appeared to be more vital than that of γδ17T cells in terms of the pathology of experimental periodontitis." (PMID 36703983, 2022). "In periodontitis, B cells initiate immune responses by producing antibodies against periodontal pathogens, and activated B cells could serve as antigen presenting cells towards CD4+ and CD8+ T cells." (PMID 34285922, 2021).